CCL5 (C-C motif chemokine ligand 5)
Diseases named in the same sentence as CCL5 in open-access papers (continued):
Sharing a sentence is not in itself a finding about the gene and the disease.
tumor (continued). "Eosinophils may promote antitumor immunity by recruiting CD8+ T cells to the tumor microenvironment via secretion of chemoattractants (CCL5, CXCL9, and CXCL10) and normalization of tumor vasculature, thereby allowing for increased effector T cell infiltration." (PMID 31730503, 2019). "We next asked if tumor-derived CCL5 is necessary for recurrence." (PMID 30990165, 2019). "Based on previous studies conducted by us and the others, a large number of tumor-infiltrating lymphocytes (TILs) correlates with increased expression of multiple chemokines CCL5 and CXCL10, capable of recruiting effector T cells, by attracting CD8+ T lymphocytes into various tumors." (PMID 31221150, 2019). "We hypothesized that tumor-derived CCL5 increases macrophage migration via activating CCR5 on macrophages." (PMID 30867568, 2019). "This was stated to indicate that the tumor cells could secrete CCL5 to enhance the T-regulatory cell suppressive function in tumor microenvironment through CCL5/CCR5 signaling and facilitate the immune evasion." (PMID 31505877, 2019). "Conversely, several previous reports limited their assessment of the effects of CCL5 expression on tumor cell behavior which could lead to biased conclusions." (PMID 31921621, 2019). "In addition, our current study suggests that the application of PD-L1 blockade can inhibit the secretion of tumor CCL5." (PMID 31221150, 2019). "Intratumoral injection of interferon could increase the expression of CXCL-10, CXCL-11, and CCL5 in tumors and help lymphocytes to localize in tumor sites to perform antitumor activities." (PMID 31662753, 2019). "Taken together these findings suggest that through IGF1R, HS6ST3 could affect both CCL5 levels and tumor infiltrating CD8+ T lymphocytes behavior." (PMID 31921621, 2019). "Given the importance of collagen for regulating tumor cell function, this may be one mechanism by which CCL5 expression accelerates recurrence." (PMID 30990165, 2019). "Taken together, in this study, the acquisition of 5FU and Dox chemoresistance in DP-HCC1806:BMMSCs is likely due to a CAM-DR mechanism, in which CD9, IL6, and CCL5/CCR5 collectively mediate tumor-growth, adhesion and anti-apoptotic signals, via integrin-dependent mechanisms." (PMID 31191817, 2019). "CCL5 promotes tumor recurrence by recruiting CCR5-expressing macrophages, which may contribute to collagen deposition in residual tumors." (PMID 30990165, 2019). "Treatments that prevent or block the release of CCL5 or that stop macrophages from supplying the residual tumor cells with collagen may help prevent recurrence." (PMID 30990165, 2019). "Both zoledronic acid and its liposomal form significantly affect the secretion of CCL5 and IL-6 in MSCs, suggesting that it could exhibit antitumor activity by affecting the ability of MSCs to interact with tumor cells and to recruit monocytes to the TME." (PMID 31096713, 2019). "Icam-1 facilitates the binding of leukocytes to vascular endothelium after extravasation, and CCL-5 is highly expressed by T-cells and can recruit leukocytes to the tumor microenvironment, indicating a pro-inflammatory function, which is increased in the absence of Pecam-1." (PMID 31344919, 2019). "In addition, the inflammatory cytokine milieu can also effect T-cell recruitment by altering sensitivity towards selectins, increasing tumor vasculature as evidenced by increased IL-6 production and by inducing T-cell chemoattractants such as CCL5 and CXCL9." (PMID 31747946, 2019). "CCL5 might influence tumor growth by regulating different tumor-infiltrating immune cells in different subtypes of BC." (PMID 31921621, 2019). "Furthermore, we assessed the CCL5 expression in tumor specimen harboring both tumor and stroma cells which provides a more accurate assessment of the CCL5 effects not only on tumor cells but also on tumor microenvironment and tumor-infiltrating immune cells." (PMID 31921621, 2019).
tumor (continued). "Upon activations, NK cells are also capable of producing a number of different cytokines/chemokines (such as IFN-γ, TNF-α, GM-CSF, MIP-1α, MIP-1β, CCL5, and RANTES) that either activate or help recruit other cell types to the tissues to shape anti-tumor or anti-microbial responses." (PMID 29867980, 2018). "The subset of genes upregulated in lungs of both tumor free and metastatic Ikkβ-deficient animals comprised Tnfa, Ccl5, Ccl17, Ccl22, Cxcl1 and Csf2, although not all changes reached significance." (PMID 29682184, 2018). "The inhibition of CCL5 secretion by cancer cells or by TME may represent an additional system to affect tumor progression." (PMID 29772686, 2018). "Consequently, relative mRNA assessment of intra-tumor cytokines revealed that 1-MT significantly reduced CCL5 (RANTES) and TGF-β, besides inhibition of IDO enzyme in comparison to PBS as showed in." (PMID 29959375, 2018). "The high expression of CCL5 in CRC patients’ tumor tissues with alcohol consumption, combined with the fact that alcohol accelerated CCL5 secretion from HT29 and DLD-1 cells, led us to the hypothesis that CCL5 may contribute to the progression of CRC." (PMID 29872080, 2018). "CCL5, a target gene of nuclear factor kappa-light-chain-enhancer of activated B cells (NF-κB), is expressed by T lymphocytes, macrophages, platelets, synovial fibroblasts, tubular epithelium, and certain types of tumor cells." (PMID 29772686, 2018). "Some studies have reported that autophagy, through which recycling of intracellular metabolites by degrading of damaged organelles and proteins takes place, is required for the motility of tumor cells, but the role of CCL5 in autophagy remains poorly understood." (PMID 29872080, 2018). "Our previous study had shown that CC chemokine ligand 5 (CCL5) could modulate the differentiation of myeloid-derived suppressor cells (MDSC) to promote tumor progression in luminal and triple-negative breast cancer." (PMID 29991744, 2018). "Because their tumor tissues displayed increased expression of C-C chemokine ligand 5 (CCL5), we hypothesized CCL5 might participate in cancer progression in such patients." (PMID 29872080, 2018). "The incompetence of the tumor microenvironment to be enriched by TAMs due to RKIP-mediated CCL5 reduction was translated into a decreased tumor cell invasiveness and secretion of pro-metastatic factors, including tumor necrosis factor receptor 2 (TNFR2) and progranulin (PRGN), by TAMs." (PMID 30149591, 2018). "Overall, decreasing cancer cells or TME secretion of CCL5 using anticancer drugs may affect both tumor cell proliferation and/or the formation of a protective/immunosuppressive TME." (PMID 29772686, 2018). "anti-VEGFR3), which may account for the modest increase in tumor growth observed in that treatment cohort as CCL5 has been shown to accelerate tumor growth in some mouse models." (PMID 29976154, 2018). "Further source of CCL5 in TME may be infiltrating leukocytes, BMSCs, mesenchymal stem cells, or tumor-associated fibroblasts." (PMID 30154786, 2018). "Here, we reported that CCL5-deficiency dramatically inhibited S100a9 secretion in CD11bhiF4/80low TAMs, which contributed to the ability of CD11bhiF4/80low TAMsCCL5−/− in promoting the infiltration of CD8+ T cells into the central tumor area." (PMID 29991744, 2018). "Notably, Sipa1−/− tumor tissue also contained a high level of Ccl5, another potential T-cell chemokine, although the Ccl5 expression was negligible in Sipa1−/− MSCs." (PMID 29500416, 2018). "Specifically, higher levels of chemokines, such as RANTES/CCL5, may recruit more leukocytes, like TAMs and DCs capable of promoting angiogenesis at the tumor site." (PMID 30613350, 2018). "The Ccl5 gene encodes CCL5, also known as RANTES, has been described as a gene expressed by activated T cells, macrophages, eosinophils, fibroblasts, epithelial cells as well as certain types of tumor cells." (PMID 29541071, 2018).
tumor (continued). "Antiangiogenic agents, such as bevacizumab, increase breast CSCs via tumor hypoxia, which might also be via up regulation of CCL5." (PMID 29861860, 2018). "Secretion of Ccl5 by such recruited CD8+ T cells may further amplify the T-cell recruitment inside the Bcr-Abl+ tumor tissue." (PMID 29500416, 2018). "Recently, a key role for intratumoral NK cells was uncovered by their production of chemoattractants, including the chemokine RANTES (also known as CCL5), that are necessary for the accumulation of cDC1 in incipient tumors and for tumor immune control in mouse models." (PMID 29904904, 2018). "Our and another researcher’s previous work have demonstrated that either tumor-derived or host-derived CCL5 could play an important role in tumor progression." (PMID 29991744, 2018). "Interestingly, in line with our results, tumor-derived OPN has been shown to induce MSC expression of CCL5 to enhance tumor growth and metastasis." (PMID 29910810, 2018). "CCR5 may also be relevant in the development of various types of cancer, as tumor cells directly secrete or induce fibroblasts to secrete CCL5, which maintain proliferation of CCR5-positive cancer cells." (PMID 29375583, 2017). "Indeed, tumor-homing eosinophils secreted chemoattractants such as CCL5, CXCL9, and CXCL10, which recruited CD8+ T cells to the tumor." (PMID 28791287, 2017). "Chemokines such as CCL2, CCL5, CCL7, CCL8, CXCL12 and growth factors, for example, M-CSF, PDGF, and VEGF aggressively recruit blood monocytes at the tumor site, where they distinguish in tumor-associated macrophages." (PMID 29450136, 2017). "In tumor lesions, the local expression of CCL5 negatively affected the expression of IGF1R." (PMID 29156819, 2017). "Moreover, in MM, it is proposed that CCL5 secreted by tumor cells contributes to disease progression mainly by its action in bone lysis." (PMID 28702457, 2017). "CCL5 belongs to the chemokine family, and it is widely established as an inflammatory chemokine secreted by many cell types including T lymphocytes, macrophages, platelets, and certain types of tumor cells." (PMID 29088737, 2017). "In both the in vitro tumor spheres and the in vivo murine model, there was a significant increase in the factors associated with M1 macrophage polarization, such as CCR5-binding chemokines (CCL3, CCL4, and CCL5), interleukins (IL-6 and IL-1β), and TNF-α." (PMID 28670313, 2017). "In that regard, however, it is interesting to note that the secretion of CCL5 induced by alisertib (so-called senescence-associated secretory phenotype) in other cancer models actually increased rather than decreased tumor infiltrating lymphocytes." (PMID 28147331, 2017). "MCF7 and MDA-MB-231 cells secrete exosomes that induce the differentiation of adipose-derived mesenchymal stem cells into myofibroblasts, increasing their secretion of factors such as SDF-1, VEGF, CCL5, and TGFβ, which are involved in regulating tumor progression and metastasis." (PMID 29197379, 2017). "In addition, tumor implants dissected at 6-weeks post-implantation demonstrated reduced Ccl5 levels, increased apoptosis (cleaved caspase-3 expression), and reduced cell proliferation (PCNA expression) in the Ccl5 KD groups." (PMID 28380429, 2017). "Our studies showed that MSCs in tumor inflammatory microenvironment secrete a number of chemokines and demonstrate that CCL5 plays a significant role in the migration of the CCA cells via CCR5, which induce AKT/NF-κB signaling activation of CCA cells that lead to metastatic growth." (PMID 29088737, 2017). "E7046 + E7777 treatment activated the innate immune system which led to an “inflamed” TME evidenced by expression of genes encoding Ccl5/RANTES, macrophage inflammatory protein-1α (MIP-1α/Ccl3), Cxcl9, Cxcl10, and Cxcl11, previously found associated with tumor destruction." (PMID 28920002, 2017).
tumor (continued). "Moreover, treatment of MSCs with supernatants from PC3 cells, leading to tumor-educated MSCs (TE-MSCs), increased the secretion of IL-6, CCL5, VEGF and FGF-2 by MSCs and increased their capability to increase PC3 cells clonogenic growth." (PMID 28477013, 2017). "Additionally, based on gene expression profiles, we revealed abnormalities in cytokines that have been reported to enhance tumor formation and progression (for example, CCL5, CXCL8 and CXCL12)." (PMID 28846080, 2017). "Tumor expression of CCL5 was reduced following [curcumin + sildenafil] treatment." (PMID 29245915, 2017). "To further understand the role of adaptive immunity in the tumor tissue, we investigated the impact of RRS on tumor weight and on immune suppression markers (Foxp3, CCL22), as well as markers for anti-tumor immunity (Granzyme B, CCL5, IFN-γ, CXCL9, CXCL10 and CXCL11)." (PMID 28603578, 2017). "Similarly, tumor cell-secreted IL6 causes Stat3 phosphorylation in lymphatic endothelial cells (LECs), inducing CCL5 expression in LECs and accelerating triple-negative breast cancer (TNBC) cell metastasis." (PMID 29197379, 2017). "To test the effects of beta blockers on the chemokine environment in tumors of RRS-exposed animals, we examined the expression of genes that are characteristic of either immune suppression (Foxp3, CCL22) or effector anti-tumor immunity (Granzyme B, CCL5, IFN-γ, CXCL9, CXCL10 and CXCL11)." (PMID 28603578, 2017). "In the tumor microenvironment, MSCs also secrete a panel of growth, immunomodulatory, and signaling molecules, such as CCL5, CCL2, TGF-β, VEGF, IL-6, and IL-10, which may play role in angiogenesis." (PMID 29268703, 2017). "As for glucose uptake, treatment of tumour cells from MMTV-PyMT.CCR5−/− mice with CCL5 did not cause an increase in ATP production (data not shown)." (PMID 27335323, 2016). "Instead, vascular defects in CCR5 null animals may be the result of defects in paracrine signaling between cancer cell CCL5 and vasculature resident in the tumor microenvironment." (PMID 27863423, 2016). "To investigate the kinetics of CCL2 and CCL5 production in the tumor microenvironment, we used the same Colon38 tumor/RT model as before and harvested tumor tissue at different timepoints post-RT, isolated RNA, and quantified the relative amounts of CCL2 and CCL5 transcript by qRT-PCR." (PMID 27852031, 2016). "CCL5 attracts leukocytes and recruits NK cells in tumor tissues." (PMID 27687589, 2016). "Additionally, genetic deletion of the Ccr5 gene or in vivo overexpression of a dominant negative form of the CCR5 ligand, CCL5, attenuated tumor formation in this model together with reduced fibroblast accumulation." (PMID 27340784, 2016). "Instead, to promote angiogenesis cancer cell CCL5 may signal directly to endothelium in the tumor-stroma." (PMID 27863423, 2016). "Surprisingly, CCR5 restoration in the BM alone was not sufficient to rescue the wild type phenotype, suggesting that impaired tumor growth associated with inhibiting CCL5/CCR5 is not due to defects in EPC biology." (PMID 27863423, 2016). "As a refinement of this approach, we then used the RANTES/CCL5 promoter to help limit NIS transgene expression to the tumor environment and thus enhance tumor specificity, based on the fact that the RANTES gene is induced in MSC when they encounter the tumor milieu." (PMID 27458162, 2016). "Notably, there is evidence that adipocytes secrete higher amounts of CCL5 in the presence of glucose and fatty acids, suggesting autocrine regulation of CCL5 in the tumour microenvironment." (PMID 27335323, 2016). "Instead findings support a mechanism by which cancer cell-derived CCL5 may directly recruit tumor vasculature from existing vasculature." (PMID 27863423, 2016). "It is thus likely that, in addition to the activation of the STING pathway to activate T cells, NF-κB may also up-regulate the T cell chemokines CCL2 and CCL5 in the tumor cells to attract T cell infiltration into the tumor microenvironment." (PMID 27014915, 2016).
tumor (continued). "Furthermore, the ligands for these receptors (CCL2 and CCL5) are often produced at increased levels by tumor tissues and, as a result, these ligands and their cognate receptors on IM have been targeted as a means to reduce tumor growth." (PMID 27852031, 2016). "CCL5 produced by MSCs and CAFs in the tumor stroma has been reported to promote cancer metastasis." (PMID 25788271, 2015). "Blockade of key factors in IFN-γ/RANTES defense loop including IFN-γ, IP-10/CXCL10, MIG/CXCL9 and RANTES/CCL5 could accelerate tumor formation and progressive dynamics of PMSB-formulated hosts." (PMID 26512920, 2015). "Ccl2 and Ccl5 have been reported to be involved in the mobilization and homing of MCs to tumor sites and to participate in the maintenance of a proinflammatory state that favors tumor growth as well as metastatic colonization." (PMID 26218064, 2015). "Cancer cells aberrantly secrete a whole battery of growth factors and chemokines such as CCL2 and CCL5 to recruit macrophages to the tumor microenvironment where they are stimulated to mature and secrete further bioactive molecules to aid processes crucial for cancer development and metastasis." (PMID 26375811, 2015). "Nonetheless, the primary samples contain a mixture of cells so that the gene expression profiling may also characterize expression from LECs that are located in the tumor and express CCL5." (PMID 26173622, 2015). "We therefore hypothesize that IL6 and CCL5 gene expression within basal cancer tumor samples may determine their metastatic potential." (PMID 26173622, 2015). "CCL5 is known to recruit macrophages at the site of the tumor." (PMID 26375811, 2015). "Since CCL5 was discovered to be up-regulated in the spleen of old mice independent of tumor burden, we don't consider it as important as the other factors for old tumor bearing mice." (PMID 26497558, 2015). "It inhibits HIV infection but also the CCL5-induced proliferation and invasion of PCa cells; this suggests that this antagonist may potentially be an effective inhibitor 9 of tumor growth and progression." (PMID 24523569, 2014). "Tumor-associated macrophages (TAMs) are derived mostly from circulating monocytes which are attracted into tumor sites by locally produced chemotactic factors, such as CCL2, CCL5, CCL7, CCL8, and CXCL12, and macrophage colony stimulating factor (M-CSF)." (PMID 24966464, 2014). "The exact functions of CCL5 in tumor biology are still unclear." (PMID 24523569, 2014). "Inhibition of CCL5 secretion by cancer cell or by the tumor microenvironment may represent an additional system to affect cancer progression." (PMID 24523569, 2014). "CCL5 serum levels correlate with the clinical stage and treatment with CCL5 promotes tumor growth." (PMID 24523569, 2014). "Treg cells migration into the tumor microenvironment is mediated by the CCL5/CCR5 axis in pancreatic adenocarcinoma, and blockade of this pathway may represent a novel immunomodulatory strategy for the treatment of cancer." (PMID 24591756, 2014). "Overall, anti-CCL5 drugs could affect both tumor cell proliferation and/or the formation of an immunosuppressive microenvironment by decreasing the secretion of CCL5 by cancer cells." (PMID 24523569, 2014). "CCL5, a target gene of NF-κB activity, is expressed by T lymphocytes, macrophages, platelets, synovial fibroblasts, tubular epithelium, and certain types of tumor cells." (PMID 24523569, 2014). "CCL5 has been tested in murine models as adjuvant therapy for tumor lysate-pulsed DC vaccines." (PMID 24967094, 2013). "CCL5 and CSF-1 are examples of monocyte-recruiting cytokines released by tumor cells." (PMID 22992343, 2012). "CCL2 and CCL5 have been shown to promote tumor cell migration and invasion." (PMID 23056468, 2012).